RHBDD1 (rhomboid domain containing 1)
Description:
Intramembrane-cleaving serine protease that cleaves single transmembrane or multi-pass membrane proteins in the hydrophobic plane of the membrane, luminal loops and juxtamembrane regions. Involved in regulated intramembrane proteolysis and the subsequent release of functional polypeptides from their membrane anchors. Functional component of endoplasmic reticulum-associated degradation (ERAD) for misfolded membrane proteins. Required for the degradation process of some specific misfolded endoplasmic reticulum (ER) luminal proteins. Participates in the transfer of misfolded proteins from the ER to the cytosol, where they are destroyed by the proteasome in a ubiquitin-dependent manner. Functions in BIK, MPZ, PKD1, PTCRA, RHO, STEAP3 and TRAC processing. Involved in the regulation of exosomal secretion; inhibits the TSAP6-mediated secretion pathway. Involved in the regulation of apoptosis; modulates BIK-mediated apoptotic activity. Also plays a role in the regulation of spermatogenesis; inhibits apoptotic activity in spermatogonia.
Synonyms: RRP4; RHBDL4; DKFZp547E052
Tractability: Antibody: UniProt predicts a signal peptide or a membrane-spanning region. PROTAC: its protein half-life has been measured.
Gene: Protein-coding gene on chromosome 2 (226,835,581 to 226,999,215, forward strand). Ensembl gene ENSG00000144468.
Subcellular location: Endoplasmic reticulum membrane; Mitochondrion membrane
Subcellular location (Human Protein Atlas): Endoplasmic reticulum
Gene Ontology:
Molecular function: protein binding; serine-type endopeptidase activity; peptidase activity
Biological process: cellular response to unfolded protein; cellular response to UV; ERAD pathway; membrane protein intracellular domain proteolysis; membrane protein proteolysis; negative regulation of apoptotic process; positive regulation of protein processing; post-translational protein modification; regulation of male germ cell proliferation; spermatid differentiation; positive regulation of protein metabolic process; retrograde protein transport, ER to cytosol
Cellular component: endoplasmic reticulum; endoplasmic reticulum membrane; endoplasmic reticulum quality control compartment; membrane; mitochondrial membrane
Genetic constraint (gnomAD): Loss-of-function variants: 32 observed, 30.07 expected, observed/expected ratio (o/e) 1.06, 90% interval 0.8 to 1.43. The upper end of that interval is the gene's LOEUF score, 1.43, which puts it in group 5 of 6, group 1 being the genes least tolerant of losing a copy. Missense variants: 322 observed, 332.86 expected, observed/expected ratio (o/e) 0.97, 90% interval 0.88 to 1.06. Synonymous variants: 129 observed, 122.4 expected, observed/expected ratio (o/e) 1.05, 90% interval 0.91 to 1.22.
Homologues: Orthologues: chimpanzee RHBDD1 (99% identical), macaque RHBDD1 (95% identical), dog RHBDD1 (87% identical), pig RHBDD1 (85% identical), rabbit RHBDD1 (85% identical), mouse Rhbdd1 (81% identical), guinea pig RHBDD1 (80% identical), rat Rhbdd1 (75% identical), tropical clawed frog rhbdd1 (57% identical), zebrafish rhbdd1 (57% identical). Paralogues in human: RHBDD2 (18% identical), RHBDD3 (17% identical).
Diseases named in the same sentence as RHBDD1 in open-access papers:
RHBDD1 is named in the same sentence as 30 diseases in open-access papers, as found by Europe PMC text mining. Sharing a sentence is not in itself a finding about the gene and the disease. The quoted sentences say what the papers report.
colorectal cancer (11 papers, 2015 to 2025). A primary or metastatic malignant neoplasm that affects the colon or rectum. "Our previous work showed that RHBDD1 expression is elevated in colorectal cancer tissue and associated with poor prognosis." (PMID 30286765, 2018). "Here we show that RHBDD1, a rhomboid intramembrane serine protease, is highly expressed and closely associated with survival in patients with colorectal cancer." (PMID 26300397, 2015). "Finally, the positive correlation of RHBDD1 expression with the EGFR/Raf/MEK/ERK signalling pathway is further corroborated in a murine model of colitis-associated colorectal cancer." (PMID 26300397, 2015). "RHBDD1 (fold change −29.99) encodes an intramembrane-cleaving serine protease that, similar to other rhomboid proteins, is involved in human cancer progression with a growth-promoting role negatively impacting patients’ survival in different cancer types (e.g., colorectal cancer and breast cancer)." (PMID 34440260, 2021). "While RHBDD1 promotes colorectal cancer (CRC) via TGFα/EGFR/ERK signaling, our study reveals a distinct mechanism in ESCC, where RHBDD1 enhances invasion by activating Wnt/β-catenin via ELK3." (PMID 40787199, 2025). "Related studies showed that RNA interference (RNA) mediated RHBDD1 silencing significantly suppressed cell proliferation and cell cycle progression in hepatocellular carcinoma, glioblastoma and colorectal cancer." (PMID 33041671, 2020). "Our findings are in accordance with previous report, suggesting that RHBDD1 can activate Wnt/β-catenin signaling pathway to promote tumor growth and metastasis in colorectal cancer." (PMID 33041671, 2020). "Our previous work revealed that rhomboid domain-containing protein 1 (RHBDD1) participates in the modulation of cell growth and apoptosis in colorectal cancer cells." (PMID 30286765, 2018). "Our lab previously found that RHBDD1 is overexpressed in colorectal cancer tumors, and EGFR was often overexpressed in many cancers." (PMID 28445956, 2017). "Our previous study showed that RHBDD1 can activate the EGFR signaling pathway to promote colorectal cancer growth." (PMID 28445956, 2017). "Here, the authors show that RHBDD1, a rhomboid intramembrane serine protease, promotes tumor growth in colorectal cancer via cleavage and secretion of TGFα, and activation of the EGFR/Raf/MEK/ERK signalling pathway." (PMID 26300397, 2015). "Furthermore, RHBDD1 is highly expressed in human cancers, such as colorectal cancer, glioblastoma, hepatocellular carcinoma, and chronic myeloid leukaemia; silencing RHBDD1 inhibits the proliferation of these tumour cells." (PMID 30483390, 2018). "In the present study, we investigated the role of RHBDD1 on EGFR in colorectal cancer." (PMID 28445956, 2017). "Based on these results, we propose that RHBDD1, a member of Rhomboids, may play a role in colorectal cancer by interacting with EGFR." (PMID 28445956, 2017). "In our previous work, we determined that RHBDD1 was highly expressed in colorectal cancer tissues but weakly expressed in adjacent normal tissues, and could activate the EGFR/Raf/MEK/ERK signaling pathway through the cleavage and secretion of TGFα as well as up-regulation of EGFR expression." (PMID 30286765, 2018). "Therefore, RHBDD1 may be useful in colorectal cancer therapy as a therapeutic target in combination with EGFR antibodies." (PMID 28445956, 2017). "In this study, we first found decreased expression of the EGFR protein following RHBDD1 knockdown in HCT116 and RKO colorectal cancer cell lines." (PMID 28445956, 2017). "Tissue microarray assays demonstrated a correlation between RHBDD1 and EGFR in colorectal cancer patients." (PMID 28445956, 2017). "Additionally, the expression levels of RHBDD1 were found to positively correlate with the activation of the EGFR/Raf/MEK/ERK signaling cascade, a crucial pathway driving colorectal cancer development." (PMID 40787199, 2025).
colorectal cancer (continued). "A tissue microarray was then used to determine RHBDD1 and EGFR expression in colorectal cancer." (PMID 28445956, 2017). "Therefore, we assessed the correlation between RHBDD1 and EGFR in colorectal cancer patient samples." (PMID 28445956, 2017). "Furthermore, the RHBDD1 and EGFR correlation was stronger in late-stage colorectal cancer patients." (PMID 28445956, 2017).
breast carcinoma (9 papers, 2018 to 2025). "In our study, we show that RHBDD1 is up-regulated in breast cancer tissue and closely associated with several important clinicopathological parameters." (PMID 30286765, 2018). "This study aimed to investigate the function of RHBDD1 in regulating breast cancer progression and its underlying molecular basis." (PMID 30286765, 2018). "In order to explore the underlying mechanisms involved in RHBDD1-driven metastasis in breast cancer cells, the effects of RHBDD1 knockdown on Akt were assessed." (PMID 30483390, 2018). "RHBDD1 was highly up-regulated in breast cancer tissue compared with that in normal tissue and associated with pathological tumor (pT) stage, pathological tumor-node-metastasis (pTNM) stage and estrogen receptor (ER) expression." (PMID 30286765, 2018). "Taken together, we proposed that the growth inhibition of breast cancer cells caused by RHBDD1 deletion may largely be attributed to RHBDD1-mediated modulation of cell apoptosis and cell cycle." (PMID 30286765, 2018). "RHBDD1 up-regulation was associated with poor prognosis in several subtypes of breast cancer." (PMID 30286765, 2018). "Consistently, in our present study, we also detected that loss of RHBDD1 could markedly increase apoptosis of breast cancer cells." (PMID 30286765, 2018). "Besides, we proposed that the inhibitory effect on breast cancer cell growth caused by RHBDD1 deletion may be attributed to increased cell apoptosis or improper cell cycle progression or both processes." (PMID 30286765, 2018). "Our study provides novel insights into the role of RHBDD1 in breast cancer and, more generally, metastasis." (PMID 30483390, 2018). "To assess the role of RHBDD1 in breast cancer, we first analysed 5 independent microarray datasets in the OncomineTM database." (PMID 30483390, 2018). "The correlation between RHBDD1 expression and relapse-free survival in PR positive breast cancer patients (n = 489, p = 0.02, log-rank test)." (PMID 30286765, 2018). "In the current study, we proved that RHBDD1 is highly up-regulated in breast cancer tissue than adjacent normal tissue." (PMID 30286765, 2018). "Taking these results together, we determined that RHBDD1 deletion increased apoptosis in breast cancer cells." (PMID 30286765, 2018). "We performed lentiviral transfection of RHBDD1-specific small interfering RNA into the breast cancer cell lines ZR-75-30 and MDA-MB-231 in order to investigate the effects of RHBDD1 deficiency on breast cancer metastasis." (PMID 30483390, 2018). "Though in-depth mechanisms remain to be elucidated, our study provides a preliminary basis to investigate RHBDD1 as a potential therapeutic target for breast cancer treatment." (PMID 30286765, 2018). "In this study, we used the OncomineTM database to determine the expression patterns of RHBDD1 in normal and breast cancer tissues." (PMID 30483390, 2018). "Consistent with the biochemical results, our immunohistochemical analysis of breast cancer tissue microarrays showed significant positive correlation of RHBDD1, p-Akt and CDK2 protein levels, indicating that these proteins have clinicopathological relevance." (PMID 30286765, 2018). "The correlation between RHBDD1 expression and relapse-free survival in ER positive breast cancer patients (n = 762, p = 0.087, log-rank test)." (PMID 30286765, 2018). "We performed immunohistochemical staining to assess RHBDD1 protein expression levels in 116 breast cancer specimens and 39 matched adjacent normal breast tissue samples." (PMID 30286765, 2018). "The correlation between RHBDD1 expression and relapse-free survival in ER and PR positive breast cancer patients (n = 467, p = 0.011, log-rank test)." (PMID 30286765, 2018). "Deletion of RHBDD1 promoted apoptosis and suppressed proliferation, migration and invasion in breast cancer cells." (PMID 30286765, 2018). "The correlation between RHBDD1 expression and overall survival in ER positive breast cancer patients (n = 109, p = 0.039, log-rank test)." (PMID 30286765, 2018).
breast carcinoma (continued). "When considering a sample having an IHC score of 5 or higher to have strong RHBDD1 expression, 94/116 (81%) of breast cancer specimens were classified as having strong RHBDD1 expression, while only 11/39 (28%) of normal tissue had strong RHBDD1 expression." (PMID 30286765, 2018). "In this study, we used lentiviral vectors to deliver RHBDD1-silencing small interfering RNAs (siRNAs) to the breast cancer cell lines ZR-75-30 and MDA-MB-231." (PMID 30483390, 2018). "Given that miR-135a targets ELK3’s 3′UTR in breast cancer, we propose investigating whether RHBDD1 transcriptionally regulates ELK3 using luciferase reporter assays." (PMID 40787199, 2025). "We found that patients with low RHBDD1 expression had better RFS or OS times in ER positive breast cancer, ER and PR positive breast cancer, HER2 positive breast cancer, PR positive breast cancer and triple negative breast cancer (the Kaplan–Meier method with log-rank testing)." (PMID 30286765, 2018). "These clinicopathological results are consistent with our in vitro data, which showed that RHBDD1 deletion remarkably inhibits breast cancer cell proliferation and migration/invasion, respectively, in both ER-positive MCF7 and Triple-negative MDA-MB-231 cell lines." (PMID 30286765, 2018). "RHBDD1-knock-out cells were established using breast cancer cell lines." (PMID 30286765, 2018). "We aimed to determine the function of RHBDD1 in breast cancer cells." (PMID 30483390, 2018). "Pairwise comparison using Spearman’s rank correlation test revealed that the protein level of RHBDD1 and p-Akt was remarkably positively correlated in breast cancer tissue (Spearman’s ρ = 0.437; p = 3.245e-05), as was that of RHBDD1 and CDK2 (Spearman’s ρ = 0.386; p = 0.0003)." (PMID 30286765, 2018). "Moreover, we observed that RHBDD1 deletion blocks G1/S phase transition and delays breast cancer cell cycle progression after synchronization with TdR." (PMID 30286765, 2018). "The expression of RHBDD1 in 2 breast cancer cell lines was examined." (PMID 30483390, 2018). "This tumor-highly expression pattern offers an important clue that RHBDD1 is important in tumorigenesis and might be used as a novel biomarker to identify breast cancer patients." (PMID 30286765, 2018). "We found that knockdown of RHBDD1 inhibited breast cancer cell migration and invasion in vitro." (PMID 30483390, 2018). "We investigated the influence of RHBDD1 silencing on breast cancer cell metastasis and invasion." (PMID 30483390, 2018). "RHBDD1 was highly up-regulated in breast cancer tissue than adjacent normal tissue (p = 1.566e-12)." (PMID 30286765, 2018). "Besides, RHBDD1 upregulation is associated with poor prognosis in ER positive breast cancer, ER and PR positive breast cancer, HER2 positive breast cancer, PR positive breast cancer and triple negative breast cancer." (PMID 30286765, 2018). "Thus, we speculate that RHBDD1 facilitates breast cancer cell migration and invasion, at least in part, by inducing EMT and regulating the Akt/NF-κB pathway." (PMID 30483390, 2018). "Previous studies have also indicated RHBDD1’s role in promoting invasion and migration in cancers such as rectal cancer, NSCLC, and breast cancer." (PMID 40787199, 2025). "Prior research has indicated that RHBDD1 also facilitates invasion and migration in various cancers, including rectal cancer, NSCLC, and breast cancer." (PMID 40787199, 2025). "Hence, targeting RHBDD1 might be a potential therapeutic strategy for breast cancer treatment." (PMID 30286765, 2018). "The correlation between RHBDD1 expression and relapse-free survival in HER2 positive breast cancer patients (n = 150, p = 0.031, log-rank test)." (PMID 30286765, 2018). "However, the function of RHBDD1 in breast cancer is unknown." (PMID 30483390, 2018). "Our data indicate that RHBDD1 overexpression may promote breast cancer metastasis via the regulation of EMT, suggesting that RHBDD1 may be an important regulator of breast cancer metastasis." (PMID 30483390, 2018).
breast carcinoma (continued). "Moreover, the protein level of RHBDD1, p-Akt and CDK2 was significantly positively correlated in breast cancer tissue." (PMID 30286765, 2018). "Our study reveals that RHBDD1 promotes breast cancer progression by regulating p-Akt and CDK2 protein levels, and might be a potential biomarker and prognostic indicator for breast cancer patients." (PMID 30286765, 2018). "Immunohistochemistry was performed to evaluate RHBDD1 expression in 116 breast cancer tissue and 39 adjacent normal tissue and expression of RHBDD1, phospho-Akt (p-Akt) and cyclin-dependent kinase 2 (CDK2) in the same 84 breast cancer specimens." (PMID 30286765, 2018).
colon cancer (4 papers, 2012 to 2023). "For this reason, we selected the knock-in approach to introduce two point mutations, G142A and S144A, into the endogenous loci of RHBDD1 in HCT116 colon cancer cells." (PMID 22624035, 2012). "In order to determine whether elevated exosome secretion caused by RHBDD1 inactivation was reproducible in other types of cells, we introduced the same mutations into endogenous RHBDD1 in RKO colon cancer cells." (PMID 22624035, 2012). "Clinically, RHBDD1 expression was positively correlated with ZEB1 at the protein level in 71 colon tumor tissues." (PMID 29426364, 2018). "The statistical analysis showed that RHBDD1 and ZEB1 exhibited a moderately positive correlation in 71 colon cancer tissues (Spearman r: 0.5312, P < 0.0001)." (PMID 29426364, 2018). "We additionally proved the positive correlation between RHBDD1 and ZEB1 at the protein level in primary colon cancer samples from patients." (PMID 29426364, 2018). "A somatic cell knock-in approach was used to genetically inactivate the endogenous RHBDD1 in HCT116 and RKO colon cancer cells." (PMID 22624035, 2012). "Also, miR-145-5p overexpression was shown to downregulate RHBDD1 by inhibiting EGFR-related signaling pathways (EGFR/Raf/MEK/ERK axis), thereby inhibiting colon cancer tumorigenesis." (PMID 36960218, 2023).
non-small cell lung carcinoma (4 papers, 2020 to 2025). A group of at least three distinct histological types of lung cancer, including non-small cell squamous cell carcinoma, adenocarcinoma, and large cell carcinoma. "Reference 1 Xu S, Zhang H, Wang A, Ma Y, Gan Y, Li G. Silibinin suppresses epithelial-mesenchymal transition in human non-small cell lung cancer cells by restraining RHBDD1." (PMID 36504376, 2022). "For instance, in non-small cell lung cancer cells, downregulation of Rhomboid domain containing 1 (RHBDD1) expressions inhibits cell growth and invasion through reducing the ZEB1/PI3K/AKT signaling pathway activation." (PMID 34539879, 2021).
colorectal tumor (3 papers, 2015 to 2018). "In this study, we found that RHBDD1 expression was positively correlated with lymphatic metastasis and distal metastasis in 539 colorectal tumor tissues." (PMID 29426364, 2018). "This was in accordance with our previous results in colorectal tumors and validated the cellular localization of RHBDD1 in tumor cells." (PMID 30286765, 2018). "The expression of RHBDD1 was analyzed in 539 colorectal tumor tissues for its correlation with lymphatic metastasis and distal metastasis." (PMID 29426364, 2018). "This phenomenon coincides with RHBDD1 promoting colorectal tumor cells undergo EMT and promoting a stem-like phenotype." (PMID 29426364, 2018). "The expression of RHBDD1 mRNA in colorectal tumor tissue and control tissues was then determined by RT–PCR." (PMID 26300397, 2015).